PTK7 (protein tyrosine kinase 7 (inactive))
Diseases named in the same sentence as PTK7 in open-access papers (continued):
Sharing a sentence is not in itself a finding about the gene and the disease.
adolescent idiopathic scoliosis (1 paper, 2021). A scoliosis with no known cause arising in adolescent. "Depletion of ptk7 is associated with both congenital scoliosis (CS) and adolescent idiopathic scoliosis (AIS) in zebrafish models." (PMID 34828397, 2021). "In this study, we analyzed variants in PTK7 identified in a mixed cohort of patients with congenital scoliosis and adolescent idiopathic scoliosis, then performed in vitro experiments to determine the effects of these variants on protein expression and sub-cellular location." (PMID 34828397, 2021). "Maternal zygotic ptk7 (MZptk7) and zygotic ptk7 (Zptk7) mutant zebrafish develop spinal curvatures that model congenital scoliosis (CS) and adolescent idiopathic scoliosis (AIS), respectively, due to differential timing of ptk7 loss-of-function." (PMID 34828397, 2021).
adrenocortical carcinoma (1 paper, 2024). "It is also unclear whether PTK7 expression has prognostic significance in adrenocortical carcinoma, but the expression of ENST00000489707.5, a preferred alternative splicing variant of PTK7, is an independent risk factor for disease-specific survival (DSS) and progression-free survival (PFS)." (PMID 39474113, 2024).
asthma (1 paper, 2014). "Our research showed that PTK7 gene was association with the occurrence of asthma in children." (PMID 24790987, 2014). "On account of regulatory impact factor (RIF) score, HAND1, PTK7, and ZIC3 were the potential asthma-related factors." (PMID 24790987, 2014). "However, further experimental verification is needed on the possible roles of HAND1, PTK7, and ZIC3 in asthma proposed in this study." (PMID 24790987, 2014). "In addition, HAND1, PTK7, and ZIC3 were found to be potential asthma-related factors considering their TIF values." (PMID 24790987, 2014). "We suggested that HAND1, PTK7, and ZIC3 may be used as biomarkers for asthma; however, more work is needed to validate our result." (PMID 24790987, 2014).
atypical teratoid rhabdoid tumor (1 paper, 2024). Atypical teratoid rhabdoid tumor (ATRT) is a highly malignant central nervous system (CNS) rhabdoid tumor (RT) found almost exclusively in children. "In atypical teratoid rhabdoid tumors (ATRT), PTK7 is also significantly overexpressed in tumor samples compared with normal brain samples." (PMID 39474113, 2024).
colon adenocarcinoma (1 paper, 2022). "PTK7 is overexpressed in colon adenocarcinoma and is a promising biomarker od aggressiveness and metastasis." (PMID 35269608, 2022).
colorectal adenocarcinoma (1 paper, 2022). The most common type of colorectal carcinoma. "Analysis with cBioPortal further revealed 15 somatic mutations affecting PTK7 protein identified within 594 colorectal adenocarcinoma samples from TCGA PanCancer Atlas data (frequency = 2.36%)." (PMID 35163215, 2022).
fibrosarcoma (1 paper, 2021). A malignant mesenchymal fibroblastic neoplasm affecting the soft tissue and bone. "Furthermore, studies analyzing HT1080 fibrosarcoma cells have implicated PTK7 in cancer cell motility and metastasis in fibrosarcoma." (PMID 34502237, 2021).
head and neck squamous cell carcinoma (1 paper, 2022). A squamous cell carcinoma that arises from any of the following anatomic sites: lip and oral cavity, nasal cavity, paranasal sinuses, pharynx, larynx, and salivary glands. "In addition, it was demonstrated that POSTN promoted the cancer stem cell (CSC)-like phenotype via the PTK7-Wnt/β-Catenin signaling pathway and enhanced proliferation and cell invasion in head and neck squamous cell carcinoma (HNSCC)." (PMID 36077762, 2022).
invasive ductal carcinomas (1 paper, 2024). "High PTK7 expression has been shown to be associated with oestrogen receptor (ER)-positive tumours in one study of 79 invasive ductal carcinomas." (PMID 39335176, 2024). "Previous research has demonstrated that high PTK7 expression was associated with ER-positive tumours in a cohort of 79 invasive ductal carcinomas, and that low PTK7 expression was associated with higher tumour grade and lymph node metastasis." (PMID 39335176, 2024).
malignant ovarian epithelial tumors (1 paper, 2024). "A study based on immunohistochemical staining analysis found significantly decreased expression levels of PTK7 from benign, intermediate, and malignant ovarian epithelial tumors and from normal controls to plasmacytoid carcinomas." (PMID 39474113, 2024).
metastatic cancers (1 paper, 2022). A carcinoma which has spread from the original site of growth to another anatomic site. "Therefore, PTK7 mAbs could be applied as therapeutics to control angiogenesis-associated diseases such as metastatic cancers." (PMID 36139622, 2022). "Therefore, we suggest that anti-PTK7 neutralizing mAbs exert therapeutic effects on aberrant angiogenesis-related diseases, including metastatic cancer, by specifically inhibiting PTK7 functions." (PMID 36139622, 2022).
neuroblastoma (1 paper, 2024). Neuroblastoma (NB) is the most common solid, extracranial childhood tumor. "In neuroblastoma, PTK7 is highly and stably expressed on the tumor cell surface, but it demonstrates low expression in normal pediatric tissues." (PMID 39474113, 2024). "Despite the lack of evidence for the direct regulatory effects of PTK7 on neuroblastoma cell fate, anti-PTK7 CAR T cells could induce antigen-specific cytotoxicity against tumors and induce tumor cell death both in vitro and in vivo." (PMID 39474113, 2024).
ovarian tumor (1 paper, 2024). "While the role of PTK7 in cancer progression garners increasing recognition, elucidating the precise molecular mechanisms governing PTK7’s impact on ovarian tumor advancement and its regulatory factors necessitates meticulous investigation." (PMID 38740744, 2024).
prostate adenocarcinoma (1 paper, 2025). "Although PTK7 was not involved in the network, we observed a significant positive correlation between the expression level of B7-H3 and PTK7 in the Cancer Genome Atlas (TCGA)–prostate adenocarcinoma (PRAD) dataset, suggesting that PTK7 may also interact with B7-H3." (PMID 40004194, 2025).
rhabdoid tumor (1 paper, 2021). An aggressive malignant embryonal neoplasm usually occurring during childhood. "Increased expression of PTK7 RNA was detected in atypical teratoid/rhabdoid tumors and repressed by PTK7 knockdown, as well as vatalanib, a tyrosine kinase inhibitor that blockades angiogenesis." (PMID 33673696, 2021).
thymic tumors (1 paper, 2020). "Compared to IL-8 assay, CD31 detection had much lower diagnostic sensitivity and specificity in distinguishing thymomas from other types of thymic tumors; PTK7 or CR2 assay also showed lower discriminatory ability in thymoma diagnosis, only with AUC level 85% and 84%, respectively." (PMID 32985506, 2020).
uterine cancer (1 paper, 2022). Primary or metastatic malignant neoplasm involving the uterine corpus and/or the cervix. "Pan-cancer TCGA analysis of PTK7 expression in the seven most common cancers in women (breast, cervical, colon, lung, ovarian, skin, and uterine cancers) revealed that PTK7 is highly expressed in all selected cancers." (PMID 35977930, 2022).
cancer (120 papers, 2010 to 2026). A tumor composed of atypical neoplastic, often pleomorphic cells that invade other tissues. "Anti-PTK7 ADCs represent an emerging therapeutic strategy targeting PTK7, a receptor implicated in cancer progression and treatment resistance." (PMID 41347223, 2025). "Here, we review the findings of previous studies and comprehensively summarize the association between PTK7 and the prognosis of patients with different cancer types." (PMID 39474113, 2024). "PTK7 is highly expressed in primary tumors and supposedly in metastatic cells but is also found in cancer-associated fibroblasts and endothelial cells." (PMID 38773263, 2024). "The diagnostic value of PTK7 is closely linked to its specific expression in cancer cells and its application in the use of aptamers." (PMID 39474113, 2024). "We report the most recent insights into the activity of PTK7, notably based on x-ray crystal structures of its pseudokinase domain, and the cancer-related pathways associated with the receptor." (PMID 38773263, 2024). "We and others have accumulated evidence that the PTK7 kinase domain is endowed with signaling functions linked to cancer despite its deficient catalytic activity, probably through signalling docking property." (PMID 38773263, 2024). "Increased PTK7 expression in diverse types of cancer has been reported, as has an association between the expression of PTK7 and tumorigenesis." (PMID 37569547, 2023). "Periostin is a matricellular protein secreted by cancer‐associated fibroblasts and the interaction between periostin and PTK7 regulates the canonical Wnt signaling pathway." (PMID 35257502, 2022). "A regulator of PCP signaling that has been implicated in cancer progression as well as NC migration is protein tyrosine kinase 7 (PTK7)." (PMID 34502237, 2021). "Expression levels of PTK7 predict a poor outcome and an increased risk for cancer metastasis in TNBC patients." (PMID 34367983, 2021). "PTK7: Another gene linking the various types of WNT signaling to cancer is the gene PTK7, an orphan receptor linked to a variety of cancers as a highly upregulated biomarker." (PMID 31382613, 2019). "Other cancer-associated genes such as Top2a, Ptn, Ptk7, Tnc and Mmp14 were highly expressed in DAKO mice." (PMID 28459858, 2017). "Recent studies have shown that overexpression of PTK7 is associated with cancer risk and that PTK7 can be used as a biomarker for predicting poor prognosis." (PMID 29261171, 2017). "The mechanism(s) underlying the contradictory roles played by PTK7 in different cancer types is unclear." (PMID 27689325, 2016). "Expression profiling in BC cell lines and primary tumors showed association of PTK7 with ER/PR/HER2-negative (TNBC-triple negative BC) cancer." (PMID 24409301, 2014). "Notably, PTK7 emerged as a significant target with high expression or survival association in seven independent cancer cohorts." (PMID 41979058, 2026). "PTK7 has been found to be strongly associated with a variety of diseases, including cancer." (PMID 39474113, 2024). "Indeed, PTK7-dependent signaling has been tightly associated with many aspects of cancer progression and identified as both a marker of poor prognosis and challenged as a promising therapeutic target in several types of cancers." (PMID 38773263, 2024). "The PTK7-targeted APDCs could directly bind to BC, and the GEM released from PTK7-GEMs could cause cancer cells collapse." (PMID 36471380, 2022). "It has been argued that PTK-7 overexpression is associated with poor prognosis in most cancers." (PMID 31820857, 2020). "Recently, Ptk7 was implicated in cancer cell motility and metastasis in fibrosarcoma HT1080 cells, identified as a potential diagnostic biomarker for a variety of cancer types, and proposed as a tumor suppressor gene by inhibiting ERK and AKT phosphorylation in lung cancer." (PMID 27438854, 2016). "PTK7 may contribute to this explaining its association with a wide range of cancers." (PMID 38474329, 2024).
cancer (continued). "As neutralizing antibodies, PTK7 mAbs specifically target PTK7-positive cells, underscoring their potential as a therapeutic agent for PTK7-positive cancers." (PMID 39936972, 2025). "To evaluate the in vivo anti-cancer effects of anti-PTK7 mAbs on TNBC, we utilized the tumorigenic potential of MDA-MB-231 cells in a xenograft mouse model." (PMID 39936972, 2025). "By combining PTK7-neutralizing antibodies with advanced ADC strategies, the treatment landscape for PTK7-positive cancers, including TNBC, would be significantly improved." (PMID 39936972, 2025). "Variants in the APCDD1, CYBA, PTK7 and SRC genes were identified in more than one family, and they were shown to dysregulate basic cellular functions, potentially leading to cancer development." (PMID 41469725, 2025). "We further evaluated PTK7 degradation in three additional cancer cell lines (MCF‐7, SUM159PT and BT474), characterized by varying sortilin expression but stable PTK7 levels, as confirmed by the HPA database." (PMID 40305781, 2025). "PTK7 is upregulated in various cancers, including BC, colon, gastric, lung, esophageal, ovarian cancers, and acute myeloid leukemia, where it regulates cell adhesion, migration, proliferation, and survival." (PMID 39936972, 2025). "Based on these findings, we assessed the anti-cancer effects of PTK7 mAbs (32-m, 43-m, 50-m, and 52-m) in a TNBC xenograft mouse model using MDA-MB-231 cells." (PMID 39936972, 2025). "The IC50 values for these cells were approximately 6-fold higher than that observed in PTK7-positive SUM159 cancer cells, demonstrating Sgc8c-M can kill PTK7-positive tumor cells with high specificity." (PMID 40987771, 2025). "A considerable portion of PTK7-related studies focuses on various cancer types, with studies in digestive system cancers comprising the largest proportion." (PMID 39474113, 2024). "As tumor-derived extracellular vesicles (EVs) have become a new hot spot in cancer research, the potential of PTK7 and PTK7-targeting aptamers for detecting extracellular vesicles has also been explored." (PMID 39474113, 2024). "Over the 21st century, the number of studies on PTK7 in cancer has increased significantly, reflecting the importance of cancer research in biomedicine." (PMID 39474113, 2024). "The molecular probe aptame-Pyropheophorbide conjugates (APCs) bind specifically to PTK7+ cancer cells and penetrate efficiently into the tumor interior, exhibiting favorable phototoxicity to target tumor cells." (PMID 39474113, 2024). "In summary, PTK7 can not only be a potential target for cancer therapy but also a biomarker for predicting the efficacy of chemotherapy and immunotherapy." (PMID 39474113, 2024). "Of the fifty of so pseudokinases in the human kinome, we focus in this review on the cell surface receptor PTK7, an evolutionary conserved tyrosine Class 1 pseudokinase receptor involved in diverse cancer-related signaling pathways, notably the WNT pathway." (PMID 38773263, 2024). "A study reported various therapeutic cargo-loadable DNA nanostructures that showed greater photodynamic activity, higher anticancer activity, and selective reduction of target proteins in PTK7+ cancer cell lines." (PMID 39474113, 2024). "Photosensitizer/Doxorubicin/Antisense oligonucleotide-loaded PA/PDN showed greater photodynamic activity, higher anticancer activity, and selective reduction of target proteins in PTK7+ cancer cells." (PMID 39474113, 2024). "would also greatly help in the design of specific inhibitors able to counteract PTK7 signaling in cancer cells." (PMID 38773263, 2024). "PTK7 also has the potential to be a biomarker used for efficacy prediction prior to cancer treatment." (PMID 39474113, 2024). "Over the past two decades, our understanding of the function of PTK7 has significantly advanced, shedding light on its role in human cancer." (PMID 39474113, 2024).
cancer (continued). "Subsequently, we will focus on the role of PTK7 in different cancer types, including its expression patterns, influence on cancer cell behavior, and potential regulatory mechanisms." (PMID 39474113, 2024). "Currently, extensive studies across various human cancer types have provided insight into PTK7 expression changes in different tissues and its preliminary clinical significance." (PMID 39474113, 2024). "PTK7 expression correlates with the fate of cancer cells and then inevitably with the clinical outcome of cancer patients." (PMID 39474113, 2024). "Among the model’s genes, PTK7 serves as a co-receptor in the Wnt signaling pathway, regulating cell polarity, movement, and migration, and is upregulated in various cancers." (PMID 39712023, 2024). "Exploring PTK7’s role in the cancer immune microenvironment is crucial for the development of PTK7-based anticancer immunotherapy." (PMID 39474113, 2024). "The drug release strategy was planned as the Sgc8c aptamers precisely targeted protein tyrosine kinase 7 (PTK7) on cancer cells, and then, NSs were taken up by the endocytosis process." (PMID 39434968, 2024). "Since its discovery, PTK7 has drawn the interest of many labs for its implication in diseases, including cancer." (PMID 38773263, 2024). "Meanwhile, the anti-PTK7 monoclonal antibodies exhibit anti-cancer activity both in vivo and in vitro." (PMID 39474113, 2024). "Further investigation should address the expression pattern of PTK7 and its signaling properties at all steps of cancer dissemination." (PMID 38773263, 2024). "GSEA was used to explore the METABRIC microarray data for enrichment of genes in the curated hallmarks of cancer gene sets in high- and low-PTK7-expressing tumours." (PMID 39335176, 2024). "PTK7-GEMs specifically bind to cancer cells dependent on the expression level of PTK7 and showed stronger anti-tumor efficacy and excellent biosafety in tumor xenograft mice models." (PMID 39474113, 2024). "In this review, we first present the current status of PTK7 research in human cancers to demonstrate the prevalence of PTK7 in various cancer types and its research progress." (PMID 39474113, 2024). "From initial expression patterns to molecular mechanisms, regulatory networks, and ongoing clinical trials of drugs, research on PTK7 in cancer has progressed through three major trends." (PMID 39474113, 2024). "As a membrane receptor overexpressed in aggressive cancers, PTK7 is currently targeted by ADC and CAR-T cell-based therapies." (PMID 38773263, 2024). "MMP-9 regulates cancer cell proliferation and metastasis in part by clearing Wnt/planar cell polarity protein-tyrosine kinase-7 (PTK7)." (PMID 38956273, 2024). "APCs bind specifically to PTK7+ cancer cells and penetrate efficiently into the tumor interior, exhibiting favorable phototoxicity to target tumor cells." (PMID 39474113, 2024). "For PTK7-targeted therapies to be a viable option for clinical cancer treatment, it is essential to enhance safety, minimize toxic side effects, and accurately identify the adaptive patient population." (PMID 39474113, 2024). "Mechanistically, in vitro experiments showed that PTK7 promotes cancer cell proliferation by modulating Ki67 and PCNA proteins." (PMID 39474113, 2024). "Given the outstanding research results of PTK7 in the field of cancer, targeting PTK7 has long been a hot research topic in the field of cancer treatment." (PMID 39474113, 2024). "As PTK7-dependent signaling can be oncogenic or tumor suppressive, PTK7-targeted ADCs were expected to be useful only for patients with cancer in which PTK7 is upregulated." (PMID 39065798, 2024). "The malignant behavior of cancer driven by PTK7 is reflected not only in its impact on patient survival but also in the association of its expression with clinicopathological characteristics." (PMID 39474113, 2024).